GINS1 (GINS complex subunit 1)
Diseases named in the same sentence as GINS1 in open-access papers (continued):
Sharing a sentence is not in itself a finding about the gene and the disease.
cancer (continued). "Combining our results and previous reports, it could be concluded that the transcription factor YB-1 promotes cancer stem cell proliferation, maintains cancer stem cell stemness, and suppresses cancer stem cell apoptosis by promoting the expression of GINS1, p21, GLP-1, Notch2, and FZD-1." (PMID 31375149, 2019). "Go-Ichi-Ni-San 1 (GINS1), an important member of the GINS family, is closely related to the occurrence and development of human malignant tumors." (PMID 39631830, 2024). "The aberrant expression of other members of GINS (GINS1, GINS2, and GINS3) occurs in different types of human cancers." (PMID 37508549, 2023). "Avoiding the limitation of the low number of samples, we collected more transcription data of GINS1 in 13 different types of cancers from another platform, GEPIA, which was based on TCGA and the GTEx database contained data of 31 cancer types." (PMID 36451247, 2022). "According to the published data, GINS1, p21, GLP-1, Notch2, and FZD-1 play important roles in the stemness of cancer stem cells." (PMID 31375149, 2019). "Research suggests that GINS1 and/or other GINS complex subunits are upregulated in some types of cancers and possess some tumorigenic characteristics." (PMID 30100882, 2018). "In summary, our current results verified that GINS1 was highly expressed in cancer patients regardless of transcription or translation and risky for survival time." (PMID 36451247, 2022). "GINS1 (a partner formed the GINS complex) not only played a crucial role under physiological conditions but was also highly expressed in cancer cells and involved in cancer proliferation and migration." (PMID 36451247, 2022). "GINS1 was strongly overexpressed in several cancer lesions compared with that in adjacent noncancerous lesions." (PMID 31755218, 2020). "We further analyzed the oncogenic functions of GINS1 in BrCa cells because this gene has not been described frequently in studies of cancer." (PMID 31755218, 2020). "In the present study, the results revealed that the transcription factor YB-1 could maintain the stemness of cancer stem cells by promoting the expression of stemness-related genes (FZD-1, p21, GLP-1, GINS1, and Notch2)." (PMID 31375149, 2019). "Noticeably, when comparing cancer samples with normal samples in HCC, GINS1 mRNA expression showed 5.203-fold elevation from Roessler Liver 2 dataset (P=6.90E-80), 4.391-fold elevation from Roessler Liver dataset (P=6.39E-10), and 5.203-fold elevation from Wurmbach Liver dataset (P=1.53E-06)." (PMID 30413605, 2018).
GINS1 also shares sentences with these, for which no sentence is quoted: lung adenocarcinoma (3 papers); Adrenal insufficiency (1); chondrosarcoma (1); chronic myelocytic leukemia (1); colorectal cancer (1); dedifferentiated liposarcoma (1); dermatitis (1); epidermodysplasia verruciformis (1); Ewing sarcoma (1); gastritis (1); gastrointestinal disease (1); herpes simplex encephalitis (1); kidney cancer (1); leiomyosarcoma (1); malignant fibrous histiocytoma (1); microcephaly (1); myxofibrosarcoma (1); non-small cell lung carcinoma (1); pancreatic cancer (1); primordial dwarfism (1); round cell liposarcoma (1); varicella (1).